PAX2 (paired box 2)
Diseases named in the same sentence as PAX2 in open-access papers (continued):
Sharing a sentence is not in itself a finding about the gene and the disease.
renal carcinoma (10 papers, 2011 to 2025). A carcinoma arising from the epithelium of the renal parenchyma or the renal pelvis. "Some studies have indicated the expression of the PAX8 and PAX2 markers in various renal carcinomas in adults, and these markers were known as useful markers in identifying kidney origin tumors." (PMID 34306127, 2021). "Previous studies have illustrated that Pax3 and Pax7 are associated with cell survival in numerous cancer cell lines and silencing of pax2 promotes renal carcinoma apoptosis." (PMID 25197636, 2014). "Pax2 and Notch signaling are also critical regulators of kidney development, and both are potential therapeutic targets in many renal cancers." (PMID 21539742, 2011). "Furthermore, it was confirmed that this approach increases apoptosis and sensitizes renal cancer cells to other chemotherapeutic drugs, suggesting that PAX2 can be an excellent target for therapeutic intervention in renal disease." (PMID 37628926, 2023). "The depletion of PAX2 by RNAi induces apoptosis in kidney carcinoma." (PMID 30942869, 2019). "Finally, one sample was positive for PAX2 in agreement with the LDA prediction as renal carcinoma." (PMID 25885340, 2015). "Moreover, these tumor cells express renal cancer markers such as PAX8, PAX2, and CD10." (PMID 40738062, 2025).
Wilms tumor (9 papers, 2012 to 2025). An embryonal neoplasm characterized by the presence of epithelial, mesenchymal, and blastema components. "The human Pax2 promoter was originally identified in fetal kidney and Wilm’s tumor, where a 1317 bp sequence demonstrated high transcriptional activity in various cell lines." (PMID 40376611, 2025). "One study showed that PAX8 was expressed in over 80% of Wilms tumor cases by immunohistochemistry, while PAX2 was present in over 90% of cases (n = 45)." (PMID 38473380, 2024). "PAX2 is considered to be a target of transcriptional suppression by the WT1 gene (Wilms tumor gene, a tumor suppressor gene)." (PMID 37628926, 2023). "The current study demonstrated PAX2 expression in 91.1% of Wilms tumor cases and PAX8 expression in 82.2% of cases." (PMID 34306127, 2021). "PAX2 is expressed aberrantly in different types of malignant tumors, such as some forms of ovarian cancer, RCC, Wilms tumors, prostate carcinomas and bladder carcinomas." (PMID 37628926, 2023). "This study aimed to evaluate the expression of PAX2 and PAX8 in Wilms tumor using immunohistochemical methods (IHC)." (PMID 34306127, 2021). "This study aimed to investigate the immunohistochemical expression of PAX2 and PAX8 in Wilms tumor for diagnosing this tumor and possibly differentiating it from other differentials." (PMID 34306127, 2021). "As in the current study, the results of these studies indicate a high frequency of PAX2 and PAX8 expression in Wilms tumor, making these markers sensitive markers for diagnosing this tumor." (PMID 34306127, 2021). "PAX2 and PAX8 expressions are also commonly detected in Wilms tumor, a pediatric kidney tumor." (PMID 38473380, 2024). "This study aimed to investigate the IHC expression of PAX2 and PAX8 in Wilms tumor." (PMID 34306127, 2021). "PAX2 and PAX8 markers might helpful in diagnosis of Wilms tumor and may differentiate it from other histologically similar kidney tumors." (PMID 34306127, 2021).
focal segmental glomerulosclerosis (8 papers, 2015 to 2025). A renal disorder characterized by sclerotic lesions in the glomeruli. "PAX2 defects have been linked to focal segmental glomerulosclerosis (FSGS)." (PMID 39408938, 2024). "The PAX2 mutation led to a thinner nephrogenic zone and decreased number of glomeruli, resulting in oligohydramnios during fetal development and oligomeganephronia and adaptive focal-segmental glomerulosclerosis in adulthood." (PMID 38139322, 2023). "Three out of five patients with PAX2 mutations had focal segmental glomerulosclerosis (FSGS) diagnosed from kidney biopsies." (PMID 26571382, 2015). "We carried out a literature review using the terms “PAX2”, “renal anomalies”, “nephrotic syndrome”, “focal segmental glomerulosclerosis”, “IgA nephropathy”, “cystic disorders” and “CAKUT” in PubMed, the MEDLINE database and Google Scholar." (PMID 37628926, 2023). "Interestingly, patients carrying a deleterious variant in PAX2 may also present with steroid resistant nephrotic syndrome (SRNS) and focal segmental glomerulosclerosis (FSGS), similar to patients with a deleterious variant in WT1." (PMID 33625646, 2021).
microphthalmia (8 papers, 2009 to 2024). Congenital or developmental anomaly in which the eyeballs are abnormally small. "Three children had PAX2-related ocular abnormalities, including nystagmus, retinal exudation, amblyopia, microphthalmia, microcornea, and total blindness." (PMID 35444690, 2022). "Single-gene deletions and mutations affecting the ability to produce proteins and enzymes such as SOX2, MFRP, ALDH1A3, STRA6, PAX2, and OTX2, have been identified as causing isolated microphthalmia and anophthalmia and syndromic forms." (PMID 30153864, 2018). "Moreover, the reduction of SOX1 expression was found in the lens of microphthalmia mutants, whereas PAX2 and PAX6 were down-regulated in the distal part of NR." (PMID 37863656, 2023). "We analyzed the expression of PAX6, PAX2, and SOX1 in microphthalmia mutants because structures expressing these proteins are missing in animals with anophthalmia, which we also see in our mutants." (PMID 37863656, 2023).
renal failure (8 papers, 2018 to 2025). ",27, 28, 29,31, 32, 33, 34, 35, 36, 37, 38 Of these, 56 carriers of a PAX2 LOF variant (54%) had kidney failure before the age of 18 years with a median age of 9.5 years (range: 2 weeks–17.5 years)." (PMID 41278353, 2025). "Monitoring PAX2 variant carriers is still relevant in adulthood because the age at kidney failure in patients with RCS with a PAX2 variant ranges from 0 to 79 years." (PMID 41278353, 2025). "In a Japanese cohort, of the seven patients with deleterious variants in PAX2 gene who progressed to renal failure in childhood, six had truncating variants." (PMID 34979951, 2022). "Genetic investigations revealed that he has inherited a mutated PAX2 gene from his father, who had renal failure at the age of 20." (PMID 30241513, 2018). "Due to severe albuminuria in most pediatric patients with CAKUT and a PAX2 variant and a median age at kidney failure of 9.5 years, close monitoring starting in infancy and antiproteinuric measures should be considered and may be particularly effective." (PMID 41278353, 2025). "Kidney failure (CKD stage G5, i.e., estimated glomerular filtration rate < 15 ml/min per 1.73 m2) before the age of 16 years occurred in 4 of 5 patients (80%) with PAX2 LOF variants who are currently ≥ 15 years." (PMID 41278353, 2025). "For example, PAX2 and PAX8 have been shown to be re-expressed in postnatal kidneys in response to acute kidney injury, nephrotoxicity, and regenerative changes." (PMID 37511191, 2023). "According to the literature, two of these differentially expressed genes, namely, paired box 2 (PAX2) [MIM: 167409] and parathyroid hormone 1 receptor (PTH1R) [MIM: 168468], are directly related to kidney failure." (PMID 36371238, 2022).
vesicoureteral reflux (8 papers, 2007 to 2025). Abnormal flow of urine from the urinary bladder back into the ureters. "PAX2 deficiency has been associated with various growth defects, such as kidney hypoplasia, optic coloboma, and vesicoureteral reflux." (PMID 37872505, 2023). "Pax2+/−;Emx2+/− mice harbor duplex systems associated with urinary tract obstruction, bifid ureter and a high penetrance of vesicoureteral reflux." (PMID 21731775, 2011). "We reported a case of the co-presence of the LMX1B and PAX2 variant in a girl with an extrarenal manifestation of Nail Patella Syndrome but also end-stage renal disease due to congenital bilateral renal hypodysplasia and vesicoureteral reflux." (PMID 36835576, 2023).
cyst (7 papers, 2011 to 2026). A sac-like closed membranous structure that may be empty or contain fluid or amorphous material. "We also found that the levels of the CWP1 protein and the cwp1, cwp2, cwp3, and myb2 mRNA and cyst formation decreased significantly in the Pax2m2 or Pax2m3 overexpressing cell line relative to the wild-type Pax2 overexpressing cell line." (PMID 22355320, 2012). "The levels of the CWP1 protein and cyst formation also increased in the Pax2 overexpressing cell line." (PMID 22355320, 2012). "Our study provides evidence for the involvement of Pax2 in DNA binding, transactivation of the cwp1-3 and myb2 genes, and induction of cyst formation of G. lamblia." (PMID 22355320, 2012). "Interestingly, overexpression of Pax2 increased the cwp1-3 and myb2 gene expression and cyst formation." (PMID 22355320, 2012). "We further investigated the effect of giardial Pax2 on cyst formation." (PMID 22355320, 2012). "Transgenic overexpression of PAX2 leads to epithelial hyper-proliferation and cyst formation." (PMID 21689023, 2011). "Whereas most cases of endometriosis strongly expressed PAX2 and were thus nonaberrant, the one case aberrant for PAX2 exhibited broad loss of PAX2 expression across the entire epithelial lining of the endometriotic cyst (100%, 2 cm cyst)." (PMID 39078313, 2025). "In this study, we found that the cyst number in the Pax2 overexpressing cell line increased by ∼2.5-fold (P<0.05) relative to the control cell line, which expresses only the puromycin selection marker (5′Δ5N-Pac), indicating that the overexpressed Pax2 can increase the cyst formation." (PMID 22355320, 2012). "Nuclear PAX2 expression, and cytoplasmic PAX8 expression were found to be up-regulated in cyst-lining epithelial cells." (PMID 41501598, 2026). "The cyst-lining epithelium expresses PAX8, PAX2, and CK7, while the subepithelial stromal region shows strong positive staining for ER, PR, CD10, Melan-A, and HMB45." (PMID 41426332, 2025). "In immunohistochemical analysis of cyst wall showing the cystic change, collecting duct markers, EMA, PAX2 and PAX8, were positive in the lining cell of the cyst wall." (PMID 25038818, 2014).
Alport syndrome (5 papers, 2020 to 2025). A rare renal disease characterized by glomerular nephropathy with hematuria progressing to end-stage renal disease (ESRD), frequently associated with sensorineural deafness, and occasionally with ocular anomalies. "Research and case reports on several FSGS patients revealed that PAX2 gene variants may contribute to the familial form of FSGS, both early and adult onset, as well as lead to glomerular basement membrane changes similar to Alport syndrome." (PMID 40282888, 2025). "We found there were no clinical features of Alport syndrome not only in six probands with c.2858G>T(p.(G953V)) in COL4A5 plus pathogenic variants in other genes (e.g., WT1, ADCK4, NPHP1, TRPC6, COL4A4, and PAX2) but also in another six probands with only the c.2858G>T(p.(G953V)) variant." (PMID 31576025, 2020).
chronic kidney disease (5 papers, 2018 to 2023). Impairment of the renal function secondary to chronic kidney damage persisting for three or more months. "Clinicians must be more alert for PAX2 mutation when facing patients with congenital kidney and urinary tract anomalies, chronic kidney disease of unknown etiology, involvement of multiple systems, and/or a family history of renal disease." (PMID 35087773, 2022). "We herein report a 3-year-old boy presented with chronic kidney disease (CKD) due to PAX2 missense mutation (C to G transversion at position 418 in exon 4)." (PMID 30241513, 2018). "Paired box 2 (PAX2)-related disorder is an autosomal dominant genetic disorder associated with kidney and eye abnormalities and can result in end stage renal disease (ESRD)." (PMID 35087773, 2022). "Single-cell suspensions obtained from needle kidney biopsy tissue of patients with chronic kidney diseases (CKD) were seeded for cell culture, yielding clones consisting of proliferative (KI67+) cells that expressed SOX9 and PAX2." (PMID 39872058, 2023).
cystic kidney disease (5 papers, 2018 to 2026). A congenital or acquired kidney disorder characterized by the presence of renal cysts. "A PAX2 mutation was identified in a patient with a prenatal diagnosis of the Potter sequence, and a postnatal ultrasound revealed renal cysts." (PMID 37628926, 2023). "In contrast, Weber’s study showed that HNF1B and PAX2 mutations caused CKDs with an age of onset between 10 and 23 years, and autosomal recessive polycystic kidney disease was reported to be the most prevalent etiology in neonatal-onset cystic kidney diseases." (PMID 34295353, 2021).
diabetes (5 papers, 2013 to 2022). "Further research is needed in order to determine if there is a relationship between PAX-2 expression and diabetes in patients with EC, if proven so, then to additionally determine the influence of metformin administration." (PMID 24308813, 2013). "All of these suggest that under diabetic mellitus, the increased growth factors and suppressed CMA with decreased degradation of Pax2 contribute to kidney hypertrophy." (PMID 35159216, 2022). "In diabetes mellitus, the CMA is decreased and the accumulation of paired-box protein (Pax2), a substrate important for renal growth, leads to kidney hypertrophy." (PMID 35159216, 2022).
endometrioid carcinoma (5 papers, 2013 to 2025). "Of 29 endometrioid adenocarcinomas, 28 (96.6%) were aberrant for at least 1 marker, with PAX2 again the most frequently aberrant." (PMID 39078313, 2025). "On the other hand, endometrioid carcinomas with PAX2 nuclear positive staining had percentage of tumor cells with positive staining from 50% to more than 75%." (PMID 23502471, 2013). "Hypomethylation, for example, produces an increase in PAX2 expression in endometrioid carcinoma." (PMID 24602166, 2014). "Thus, the expression of PAX2 in clear cell and endometrioid carcinomas were significantly higher than that of serous carcinomas (9%) that we had reported previously." (PMID 23502471, 2013). "Alterations in the immunohistochemical characteristics of ER, PTEN, PAX8, and PAX2 were noted in PDXs and their passages regardless of the parental tumor phenotypes, i.e., endometrioid carcinomas and carcinosarcomas." (PMID 37231035, 2023).
renal fibrosis (5 papers, 2012 to 2024). A final common manifestation of a wide variety of chronic kidney diseases characterized by glomerulosclerosis and tubulointerstitial fibrosis. "Small interfering RNA (siRNA) targeted paired box2 (PAX2) was reported to be delivered to the kidney with PEI nanoparticles via an intrarenal capsule injection in a mouse model of renal fibrosis induced by UUO." (PMID 30410705, 2017). "PAX2–siRNA–PEI nanoparticles inhibited PAX2 mRNA and PAX2 protein in the kidney, and ameliorated renal fibrosis." (PMID 30410705, 2017). "Although not investigated here, mechanisms involving TGF-β signalling, and suppressed expression of PAX2 might also be the case in renal fibrosis, where a role for PAX2 expression in kidney injury has also been identified." (PMID 29928489, 2018). "The contribution of ADAM10 over-expression to PAX2-induced EMT deepens our understanding of renal fibrosis and may inform development of anti-fibrogenic strategies." (PMID 30117015, 2018). "Following kidney injury, generation of renal fibrosis or scar tissue is dependent on the expression of TGF-β and eventually, EMT-dependent suppression of PAX2 expression following its transient activation." (PMID 29928489, 2018). "In summary, our findings shed light on the mechanism of PAX2-induced EMT and renal fibrosis and the up-regulation of ADAM10." (PMID 30117015, 2018). "As PAX2 was observed to induce EMT in renal tubular epithelial cells, and PAX2 could regulate ADAM10 in several cell types, we hypothesized that PAX2 may regulate ADAM10 activity in the renal tubular epithelia, and that ADAM10 might be implicated in the pathogenesis of EMT and renal fibrosis." (PMID 30117015, 2018). "PAX2 directly increased expression of ADAM10, the presence of which contributed to EMT in renal tubular epithelia and hence plays an important role in renal fibrosis." (PMID 30117015, 2018). "Our results, for the first time, indicate that PAX2 promotes EMT in the renal tubular epithelia via directly activating ADAM10, and that ADAM10 participates in the pathogenesis of renal fibrosis." (PMID 30117015, 2018). "In the current study, we investigated the influence of ADAM10 on PAX2-induced EMT in renal tubular epithelia and the effect of ADAM10 in renal fibrosis." (PMID 30117015, 2018).
serous ovarian carcinoma (5 papers, 2013 to 2020). "The loss of PAX2 expression in SCOUTs and, although still controversial, its frequent loss in high-grade serous ovarian cancers underpin the need to better understand the biological cause and consequences of loss of PAX2 expression in OVE cells." (PMID 29100356, 2017). "Potentially, the frequent loss of PAX2 in SCOUTs, STICs and high-grade serous ovarian cancers is essential to allow for the stem cell-like plasticity required for tumor progression." (PMID 29100356, 2017). "In serous ovarian carcinoma, down-regulation of PAX2 expression during later stages of tumor development in secretory cell outgrowths (SCOUTs) has been identified, and members of the TGF-β downstream signalling pathway were expressed in the same cells." (PMID 29928489, 2018). "For example, PAX2 protein expression has been noted at relatively early stages of tumor formation in serous ovarian carcinoma, but at later stages of progression the acquisition of metastasis is accompanied by loss of PAX2 expression." (PMID 29928489, 2018). "In serous ovarian cancer, the down-regulation of PAX2 expression occurs in the secretory outgrowths (termed SCOUTs), in which aggressive changes have been documented to occur." (PMID 29928489, 2018). "The gene expression level of PAX2 was estimated from microarray data, which indicated that non-serous ovarian carcinomas also had a higher gene expression of PAX2." (PMID 23502471, 2013). "Interestingly, ectopic expression of PAX2 in the STOSE model of high-grade serous ovarian cancer led to delayed tumor formation and reduced dissemination." (PMID 29100356, 2017). "Immunostaining of PAX2 was performed on paraffin sections from 55 non-serous ovarian carcinomas." (PMID 23502471, 2013). "PAX2 was found to be highly expressed in mostly non-serous ovarian cancer cell lines." (PMID 23502471, 2013). "A recent study reported that PAX2 is expressed in 100% of serous ovarian carcinoma cases; however, this is not supported by previous studies which reported that as low as 9% of these cancers express PAX2." (PMID 29100356, 2017). "Two PAX2 negative serous ovarian cancer cell lines (OVCAR3 and OVCA432) after transfected with pCMV6-Myc-PAX2, cell proliferation was significantly suppressed in comparison to the vector transfection control." (PMID 23502471, 2013).
clear cell renal cell carcinoma (4 papers, 2014 to 2025). "Pax2 downregulation has been shown to lead to growth inhibition of cancer cells, and reactivation of Pax2 is also observed in clear cell renal cell carcinoma, a tumor type characterized by loss of VHL tumor suppressor function." (PMID 34195082, 2021). "Herein, we reported a retroperitonal DSFT with unexpected CK-pan and Pax-2 expression, mimicking high-grade clear cell renal cell carcinoma." (PMID 40432917, 2025).